CAPG (capping actin protein, gelsolin like)
Diseases named in the same sentence as CAPG in open-access papers (continued):
Sharing a sentence is not in itself a finding about the gene and the disease.
tumor (continued). "CAPG plays an important role both in the immune response and tumor progression." (PMID 38069262, 2023). "The staining of CAPG was low in tumor tissue but undetectable in normal tissue." (PMID 36233273, 2022). "Besides, MST1R (AUC = 0.811), CAPG (AUC = 0.743), CLEC18A (AUC = 0.714), and EMT score (AUC = 0.700) also had significant diagnostic accuracy in distinguishing tumor and normal samples." (PMID 36072903, 2022). "Our investigations identified three major invasiveness biomarkers not documented so far in integrative molecular studies characterizing MM, common to the three tumor sources, CAPG, FABP4, and LAMB2, and an additional set of candidate biomarkers shared by rat and patient tumors." (PMID 32867073, 2020). "We found CapG overexpression promoted MCF-7 xenograft tumor growth." (PMID 31660072, 2019). "We also found that knockdown of the expression of CapG reduced tumor migration." (PMID 30155403, 2018). "Our data illustrates that CapG was overexpressed in the metastatic CRC cases, suggesting that CapG may contribute on tumor metastasis in human CRC." (PMID 30155403, 2018). "It suggests that CapG might play an important role in migration as well as tumor invasion also in OC." (PMID 24804218, 2014). "Thus, the cutoff for CapG overexpression in tumor samples was set at a 2.0-fold increase of CapG expression compared to the mean expression level in the control probe set." (PMID 24804218, 2014). "Interestingly, higher expression of CapG was observed in the tumor margin where invasive cells are located, pointing to a role for CapG in tumor cell dissemination and metastasis." (PMID 24330716, 2013). "Indirect evidence suggests that CapG is involved in tumor cell dissemination and metastasis." (PMID 24330716, 2013). "CapG protein expression was correlated with OSCC tumor size (P = 0.014)." (PMID 18237446, 2008). "In addition, those investigators showed that CapG protein expression reduces the ability of a transformed cell to induce tumour formation, suggesting that CapG is a tumour suppressor gene." (PMID 18237446, 2008). "However, accumulating evidence has indicated a number of theories on the possible function of CapG as a tumor activator." (PMID 18237446, 2008). "On the other hand, CAPG may also be involved in the movement and migration of tumor cells." (PMID 38700746, 2025). "In tumor cells, the expression and function of CAPG may change." (PMID 38700746, 2025). "Second, although our xenograft models consistently demonstrated that CAPG knockdown enhanced Dox sensitivity, variations in tumour microenvironment, immune infiltration, and metabolic heterogeneity across different animal batches could potentially influence the reproducibility of these results." (PMID 40982354, 2025). "In addition, the expression and function of CAPG in different types of tumors and tumor cells may vary." (PMID 38700746, 2025). "To further detect whether this polypeptide CAPG-171aa plays a role in promoting the growth of TNBC, we subcutaneously implanted stably expressed OE-CAPG-171aa MDA-MB-231 cell line into BALB/c nude mice, and the results showed that OE-CAPG-171aa promotes tumor growth." (PMID 37408008, 2023). "Herein, our data suggested that CapG might be a prognostic marker for metastasis but could not be used as a diagnostic tumor marker for CRC patients." (PMID 30155403, 2018). "Moreover, our in vitro study demonstrated that CapG might contribute on tumor metastasis in human CRCs." (PMID 30155403, 2018). "CapG, a membrane of the gelsolin family, has the common property of binding to the barbed end of actin filaments with high affinity and has been identified as playing important roles in tumor invasion and metastasis including breast, lung, and prostate carcinoma." (PMID 30155403, 2018).
tumor (continued). "In case CapG phosphorylation at Ser337 affects cell motility and invasiveness, the CapG Arg335 variant with intact PKC phosphorylation recognition site may be relevant for migration of tumor cells from fallopian tubes into the ovaries." (PMID 24804218, 2014). "Interference with MLKL decreases capping actin protein (CAPG) content, confirming that MLKL/CAPG-induced necroptosis significantly reduces tumor volume in mice." (PMID 38164173, 2024). "CAPG participating in immune escape was identified as a poor prognostic gene for LGG patients, of which its higher expression was found in tumor tissues versus that in normal tissues." (PMID 36233273, 2022). "In fact, high expression of gelsolin, CapG, Stathmin, CCT8 and Rho GTPases have all been described to promote tumor cell migration, invasion and formation of metastases in various tumor entities." (PMID 32545200, 2020). "CAPG, together with ANXA5 and FABP4, was previously found within a group of biomarkers differentiating invasive from noninvasive MM rat tumor models, their abundance being very significantly increased and decreased, respectively." (PMID 32867073, 2020). "Among others, overexpression of serpin H1, F-actin capping protein subunit beta (CAPZB), macrophage capping protein (CAPG), villin 2 (EZR), and cathepsin B (CTSB) are known to promote cell motility and invasion in tumor tissues." (PMID 21305022, 2011). "The expression of CLU, ITGB3, CAPG, and PRAME was investigated to study differences in expression levels between tumours from survivors and tumours from deceased patients." (PMID 19775429, 2009). "The proteins CLU, ITGB3, CAPG, and PRAME were examined with western blot for semiquantitative measurements of each protein in 98 tumours." (PMID 19775429, 2009). "A significant difference in expression between tumours from survivors and tumours from deceased patients was detected for ITGB3 (p = 0.005), but not for the other proteins, CLU (p = 0.15), PRAME (p = 0.62), and CAPG (p = 0.24)." (PMID 19775429, 2009). "Our previous analysis demonstrated differences in expression between tumours from survivors and tumours from deceased patients, including four cancer-related genes, ITGB3, CLU, CAPG, and PRAME." (PMID 19775429, 2009). "Abnormal expression of CAPG in UCEC may alter cell proliferation and invasion owing to DNA methylation or miRNA changes, and high CAPG level may participate in tumor progression by influencing the TME to regulate the immune response and ferroptosis." (PMID 39600941, 2024). "In addition, genes related to tumor spreading, cell migration, and cytoskeletal reorganization were also up-regulated in vitro and in vivo, such as CDC42, DNMBP, CAPG, NRAS, BCL9L, etc.." (PMID 39063079, 2024). "The gene expression levels of CAPG, CLEC18A, and MST1R were higher in the tumor samples." (PMID 36072903, 2022). "Although CAPG expression levels of normal tissues and tumor tissue without venous invasion were identical, its expression markedly upregulated in tumor tissue with vascular invasion compared to those without vascular invasion." (PMID 34109210, 2021). "Moreover, while paclitaxel effectively inhibited the tumor growth in mice implanted with control cells, it barely reduced tumor growth in mice transplanted with MCF-7/CapG cells, indicating a paclitaxel resistance-promoting effect of CapG." (PMID 31660072, 2019). "Our in vitro study suggests that CapG could be used as a biomarker for metastatic CRC in the clinical specimens and might play a role in tumor metastasis." (PMID 30155403, 2018). "As we observed a common overexpression of SEPTIN9 and CAPG at the protein level in dormant cells regardless of the tumour type, we investigated a potential functional impact by measuring the physical properties of the dormant cells compared to their parental counterpart cells in both MRD models." (PMID 39223638, 2024). "Moreover, silencing of CapG reduced tumour invasion without affecting the proliferation of the HCC cells." (PMID 24205396, 2013).
tumor (continued). "Consequently, the insignificant results for CLU, CAPG, and PRAME in the present study highlight the importance of verifying data in an external validation set of tumours, although, the number of tumours analysed with QPCR in this study was low, and small groups may have had an impact on the results." (PMID 19775429, 2009). "Additionally, we examined CAPG expression in 77 paired HCC and adjacent non-tumor tissues using tissue microarrays analysis, confirming its overexpression in tumor samples." (PMID 40959275, 2025).
infection (5 papers, 2010 to 2022). The state of being infected such as from the introduction of a foreign agent such as serum, vaccine, antigenic substance or organism. "In contrast, the clones with undetectable CAPG expression generally showed normal infection levels with a significant difference observed only at the 24 h time point for clone #6." (PMID 36146710, 2022). "CAPG consists of about 1% of total protein in macrophages, cells that are primary targets of infection and effectors of EBOV disease." (PMID 36146710, 2022). "Taken together, our initial tests indicated a role for CAPG in controlling steps early in infection as well as egress but having a greater impact on virus yield from infected cells." (PMID 36146710, 2022). "CAPG may be involved in regulation of actin microfilament remodeling which is required for Salmonella invasion at the early stage of infection." (PMID 21172007, 2010). "The fluorescence of infected MDA-MB-231 cells was quantified in three independent infection experiments, showing a clear increase in the blue/green 450/520-nm fluorescence ratio with EPEC quad bacteria carrying T3s-Bla fusions of GFP or CapG nanobodies." (PMID 24330716, 2013).
adenocarcinoma (2 papers, 2016 to 2024). A common cancer characterized by the presence of malignant glandular cells. "CAPG was stronger in the deep infiltrating than in the superficial mucosa of highly differentiated adenocarcinoma and CAPG was stronger in the deep infiltrated than superficial mucosa of hypodifferentiated adenocarcinoma." (PMID 38191512, 2024).
endocrine system disorder (1 paper, 2010). A disease involving the endocrine system. "IPA data base showed RETNLB and FDPs were associated with endocrine system disorders; CAPG, ACOT9, FDPS, and IMPDH2 were associated with genetics disorder." (PMID 21172007, 2010).
heart disease (1 paper, 2022). "Recently, a ROCK inhibitor was shown to indirectly decrease CAPG expression in fibroblast cells and resulted in improved wound healing in heart disease models." (PMID 36146710, 2022).
metabolic disease (1 paper, 2025). A congenital disorder (due to inherited enzyme abnormality) or acquired (due to failure of a metabolically important organ) disorder resulting from an abnormal metabolic process. "In the lncRNA-miRNA-mRNA network, NEAT1 regulates CAPG/DDAH2 through miR-1179/miR-1276, which is consistent with previously reported pivotal roles of NEAT1 in inflammation and metabolic diseases." (PMID 41050938, 2025).
CAPG also shares sentences with these, for which no sentence is quoted: breast tumors (2 papers); anemia (1); autism spectrum disorder (1); Bacterial Infections (1); cholangiocarcinoma (1); clear cell renal cell carcinoma (1); colon cancer (1); heart failure (1); Hodgkins lymphoma (1); Hurler syndrome (1); Infertility (1); Intellectual disability (1); kidney cancer (1); kidney stone (1); leukemia (1); liver fibrosis (1); lung adenocarcinoma (1); malignant mesothelioma (1); metastatic tumors (1); mononucleosis (1); neuropathy (1); Obesity (1); ocular melanoma (1); ovarian tumor (1); pneumonia (1); promyelocytic leukemia (1); pulmonary hypertension (1); renal cell carcinoma (1); renal tumours (1); small cell lung carcinoma (1).
A further 3 diseases each share a sentence with CAPG in 1 paper.